KLF5 (KLF transcription factor 5)
Description:
Transcription factor that binds to GC box promoter elements. Activates the transcription of these genes.
Synonyms: BTEB2; CKLF; IKLF
Tractability: Small molecule: a high-quality ligand is known; it belongs to a druggable protein family. PROTAC: UniProt records ubiquitination sites on it; ubiquitination databases record sites on it; a small molecule that binds it is known.
Target class: Transcription factor
Chemical probes: ML264
Gene: Protein-coding gene on chromosome 13 (73,054,976 to 73,077,541, forward strand). Ensembl gene ENSG00000102554.
Subcellular location: Nucleus
Subcellular location (Human Protein Atlas): Nucleoplasm; Golgi apparatus; Vesicles
Pathways (Reactome):
Developmental Biology: Transcriptional regulation of granulopoiesis; Transcriptional regulation of white adipocyte differentiation
Gene Ontology:
Molecular function: DNA-binding transcription activator activity, RNA polymerase II-specific; protein binding; RNA polymerase II cis-regulatory region sequence-specific DNA binding; sequence-specific double-stranded DNA binding; DNA-binding transcription factor activity, RNA polymerase II-specific; DNA binding; DNA-binding transcription factor activity; MRF binding; sequence-specific DNA binding
Biological process: positive regulation of transcription by RNA polymerase II; regulation of transcription by RNA polymerase II; cellular response to endothelin; positive regulation of cell population proliferation
Cellular component: nucleoplasm; nucleus; chromatin; transcription regulator complex
Genetic constraint (gnomAD): Loss-of-function variants: 9 observed, 30.26 expected, observed/expected ratio (o/e) 0.3, 90% interval 0.18 to 0.52. The upper end of that interval is the gene's LOEUF score, 0.52, which puts it in group 2 of 6, group 1 being the genes least tolerant of losing a copy. Missense variants: 517 observed, 530.73 expected, observed/expected ratio (o/e) 0.97, 90% interval 0.91 to 1.05. Synonymous variants: 240 observed, 213.47 expected, observed/expected ratio (o/e) 1.12, 90% interval 1.01 to 1.25.
Homologues: Orthologues: chimpanzee KLF5 (99% identical), rabbit KLF5 (97% identical), dog KLF5 (96% identical), pig KLF5 (95% identical), rat Klf5 (91% identical), mouse Klf5 (89% identical), guinea pig KLF5 (78% identical), tropical clawed frog klf5 (69% identical), zebrafish klf5a (51% identical), zebrafish klf5b (39% identical), Drosophila melanogaster luna (24% identical), Drosophila melanogaster CG3065 (12% identical). Paralogues in human: KLF7 (24% identical), KLF12 (24% identical), KLF4 (24% identical), KLF6 (23% identical), KLF2 (23% identical), KLF3 (23% identical), KLF8 (22% identical), KLF1 (21% identical), KLF11 (20% identical), SP8 (19% identical), KLF10 (19% identical), KLF15 (19% identical), and 10 more.
Diseases named in the same sentence as KLF5 in open-access papers:
KLF5 is named in the same sentence as 210 diseases in open-access papers, as found by Europe PMC text mining. Sharing a sentence is not in itself a finding about the gene and the disease. The quoted sentences say what the papers report.
breast carcinoma (134 papers, 2009 to 2026). "This study sought to assess the biological function of lncRNA SNHG15 and investigate the underlying mechanisms involved in SNHG15/miR-153-3p/KLF5 signal axis in breast cancer (BC)." (PMID 40959095, 2025). "KLF5, a transcription factor associated with basal-type breast cancer stem cells, has also been shown to be a target of metformin." (PMID 38543182, 2024). "Three DUBs, including ATXN3L, BAP1, and USP3 can deubiquitinate and stabilize KLF5 that are implicated in the pathological development of breast cancer." (PMID 38468288, 2024). "High expression of KLF5 was associated with worse distant metastasis‐free survival and overall survival of breast cancer patients in public database cohorts." (PMID 36529697, 2023). "KLF5 has been shown to be upregulated and associated with poor prognosis and promotes breast cancer cell growth and invasion by activating the expression of various oncogenes and downstream signalling pathways." (PMID 37461162, 2023). "A large number of studies have implicated KLF5 as an oncogene in several cancer tissues, particularly in colorectal, pancreatic, and breast cancer." (PMID 38087142, 2023). "BRCA1-associated protein 1 (BAP1) stabilizes KLF5 by removing the ubiquitin chain, thereby promoting the occurrence and metastasis of breast cancer." (PMID 36613989, 2022). "Previous studies have shown that high expression levels of KLF5 are significantly associated with an increased risk of recurrence and poor prognosis in breast cancer patients." (PMID 35342356, 2022). "KLF5 is present primarily in the epithelial cells lining the bases of the crypts and has been linked with cisplatin resistance in breast cancer." (PMID 30478887, 2019). "We show that Supervised mode significantly increases statistical power and identifies additional GRNs and associated Master Regulators, such as SOX11 and KLF5 in Basal-like breast cancer." (PMID 30364927, 2019). "In this regard, higher KLF5 expression associated with the TN status of breast cancer, and more specifically, KLF5 expression was higher in the basal A than basal B subtype of TNBC, which inversely correlated with TTK expression." (PMID 30206215, 2018). "KLF5 is an important transcription factor associated with many human cancers, such as breast cancer, gastric cancer, colorectal cancer, bladder cancer and prostate cancer." (PMID 28032601, 2017). "Conversely, several studies have demonstrated that KLF5 promotes breast cancer cell proliferation and survival and KLF5 expression has been associated with decreased breast cancer survival rates." (PMID 23372710, 2013). "Besides UCHL1, some other DUBs, such as ATXN3L, BAP1, and USP3 can deubiquitinate KLF5 and are implicated in the pathological development of breast cancer." (PMID 38468288, 2024). "The expression of HDAC1 and KLF5 is positively associated with breast cancer." (PMID 36230903, 2022). "For instance BAP1 deubiquitination modified the transcription factor KLF5 in breast cancer cells promotes the growth of tumor cells, and the proliferation and invasion of tumor cells are weakened after BAP1 knocking down." (PMID 40918144, 2025). "CircROBO1 promotes the development and liver metastasis of breast cancer through the circROBO1/KLF5/FUS feedback loop." (PMID 41229443, 2025). "Consistently, the mRNA expression levels of XPO1 and KLF5 are positively correlated in breast cancer clinical samples, particularly in BLBC patients." (PMID 39888288, 2025). "USP3 is dependent on KLF5 and ectopic expression of KLF5 partially rescues the proliferation inhibiting effect of USP3 knockdown in breast cancer cells in vitro and tumorigenesis in vivo." (PMID 38773075, 2024). "USP3 promotes gallbladder cancer proliferation by modifying the deubiquitination level of pyruvate kinase L/R, and USP3 facilitates breast cancer progression through KLF5 deubiquitination." (PMID 38531846, 2024).
breast carcinoma (continued). "This research unveils a new mechanism through which HDACis suppress basal-like breast cancer, highlighting an innovative interaction between KLF5 protein acetylation and ubiquitination." (PMID 38822399, 2024). "The study also identified KLF5 as a potent target for inhibiting breast cancer metastasis, with inhibitors that effectively inhibit the migration ability of breast cancer cell lines." (PMID 39294728, 2024). "In a case of molecular subtype, studies have shown that HDACis facilitate the ubiquitination and degradation of KLF5 in basal-like breast cancer." (PMID 38822399, 2024). "Research indicates that TAZ/YAP can counteract WWP1-mediated KLF5 degradation, thereby promoting breast cancer cell proliferation and tumor development." (PMID 39949609, 2024). "For instance, BAP1’s role in the deubiquitination of KLF5 encourages the progression of breast carcinoma." (PMID 37573347, 2023). "Analysis by the breast cancer database (bc-GenExMiner v4.5) showed a positive correlation between EphA2 and KLF5 in basal-like patients (R=0.30, n=783) and all breast cancer patients (R=0.36, n=4421)." (PMID 37063424, 2023). "By enhancing the epithelial-mesenchymal transition, the FUS/circEZH2/KLF5 feedback loop promotes CXCR4-induced liver metastasis of breast cancer." (PMID 37670963, 2023). "Among these metastasis‐related hub genes, KLF5 was identified and validated as an effective target for inhibiting breast cancer metastasis." (PMID 36529697, 2023). "KLF5’s proliferative and pro-survival effects are mediated by IGFL2-AS1, and KLF5 promotes basal-like breast cancer by upregulating the expression of IGFL1 and cell growth and survival." (PMID 37893009, 2023). "We previously reported that FGF-BP1 is a transcription target of Krüppel-like Factor 5 (KLF5) transcription factor in basal-like breast cancer." (PMID 37838174, 2023). "The high expression level of KLF5 has been reported to be an independent poor prognostic marker in breast cancer." (PMID 38087142, 2023). "As revealed by transwell migration assay, the metastatic ability of MDA‐MB‐231 and MCF‐7 breast cancer cells was greatly decreased after being treated with KLF5 inhibitor ML264." (PMID 36529697, 2023). "A recent study showed that BAP1 forms a complex with the transcription factor KLF5 to stimulate cell cycle progression and promotes breast cancer cell proliferation by deubiquitinating and stabilizing KLF531." (PMID 36754982, 2023). "YAP and TAZ can also inhibit WWP1-mediated KLF5 degradation, leading to breast cancer proliferation (Fig. 5A3,)." (PMID 38129384, 2023). "In KLF5-positive breast cancer cells, BAP1 reduced p27 expression and promoted cell proliferation in vitro." (PMID 35884607, 2022). "Our previous study found that KLF5 was essential for maintaining the stemness of normal breast stem cells and BCSCs in basal-like breast cancer (BLBC)." (PMID 36230903, 2022). "KLF5 is highly expressed in basal breast cancer, and inhibiting KLF5 expression can hinder breast cancer cell migration and proliferation in vitro and tumorigenesis in vivo." (PMID 36340269, 2022). "KLF5 has been verified to act as an oncogene in gastric cancer, breast cancer, leukemia, bladder cancer, and ovarian cancer." (PMID 35836107, 2022). "Both Yes-associated protein (YAP) and TAZ antagonized degradation of KLF5 by WWP1, resulting in enhancement of proliferation of breast cancer cells." (PMID 34226507, 2021). "Our result demonstrated that lncRNA LINC00152 plays a vital role in breast cancer tumor growth and proliferation in a KLF5-mediated manner." (PMID 33842324, 2021). "It has been shown that BAP1 promotes the development of breast cancer by releasing the ubiquitin modification of the transcription factor human Krüppel‐like factor 5 (KLF5)." (PMID 33529461, 2021). "To determine the exact role of KLF5 in LINC00152-mediated breast cancer growth, we detected the expression of KLF5 at mRNA and protein level in LINC00152 knockdown breast cancer cells." (PMID 33842324, 2021).
breast carcinoma (continued). "At the same time, ATXN3 deubiquitinates and stabilizes KLF4, a closely related member of KLF5, enhancing cell migration and lung metastasis in breast cancer." (PMID 34575114, 2021). "In human breast cancer, BAP1 functions as deubiquitinase to stabilize the transcription factor KLF5—which is highly expressed in basal-like breast cancer—and promotes breast cancer cell proliferation, migration, and tumor growth." (PMID 33483476, 2021). "BAP1 interacted with KLF5 and led to its stability and exerted its oncogenic function in breast cancer." (PMID 34226507, 2021). "This KLF5‒FGF-BP interaction is also involved in Yes-associated protein (YAP)-mediated tumorigenesis and angiogenesis in breast cancer." (PMID 33493334, 2021). "It was reported that androgen‐induced KLF5 expression in human breast cancer cell lines and a prodrug of 17β‐oestradiol inhibited KLF5‐NFκB inflammatory pathway in the Alzheimer's Disease mouse model." (PMID 33523554, 2021). "The transcriptional regulator, Krüppel-like factor 5 (KLF5), performs protumorigenic activity in breast cancer via interacting with critical survival pathways." (PMID 34575114, 2021). "By using Jaspar, we firstly identified two binding sites of KLF5 on the LINC00152 promoter in breast cancer." (PMID 33842324, 2021). "USP3 is also responsible for the stabilization of Klf5 that inhibits cell cycle inhibitor p27, promoting cellular proliferation in breast cancer HCC1937, HCC1806 and SUM149PT cells." (PMID 34577547, 2021). "In conclusion, these results demonstrated that LINC00152 facilitate the breast cancer cell proliferation and tumorigenicity through KLF5." (PMID 33842324, 2021). "A recent study demonstrated that transcription factor KLF5 promotes the migration of breast cancer cells partly by upregulating M-Sec." (PMID 32650782, 2020). "Paradoxically, KLF5 has been shown to have a tumour suppressor role in oesophageal squamous cell carcinoma and breast cancer." (PMID 32880368, 2020). "In other contexts, KLF5 has been shown to cooperate with TEAD transcription factors, downstream of YAP/TAZ and KLF5 is stabilised by YAP in breast cancer cells." (PMID 32880368, 2020). "High expression levels of KLF5 are a determinant of resistance to cisplatin in ovarian and breast cancers and corresponded with enhanced EGFR signaling in both colorectal cell lines." (PMID 30478887, 2019). "In breast cancer, for example, KLF5 promotes cell proliferation, migration and invasion by up-regulating expression of TNFAIP2." (PMID 31327760, 2019). "In pancreatic, bladder, intestine, colon, and breast cancers, KLF5 enhances cell proliferation, survival, and invasiveness, which is deemed to be an oncogene." (PMID 31178864, 2019). "For breast cancer, lncRNA Pvt1, which was ranked in top 5%, was validated to regulate triple-negative breast cancer through KLF5/beta-catenin signalling." (PMID 31787106, 2019). "In that regard, previous studies showed that KLF5 promotes breast cancer cell migration and invasion by upregulating transcription of TNFAIP2, and that KLF5 controls keratinocyte migration via the integrin-linked kinase." (PMID 31327760, 2019). "In our study, we showed that EYA2 was associated with CSCs markers YBX1, KLF5, and SOX10 in breast tumor tissues, and EYA2 overexpression up-regulated YBX1 in breast cancer cell lines." (PMID 30761270, 2019). "For example, target genes of BAP1 deubiquitination include mutant ATRX in myeloid neoplasms and Krüppel-like factor 5 (KLF5) in basal-like breast cancers, which both become stabilized by BAP1 and consequently accelerate tumor growth." (PMID 31903168, 2019). "Metformin has been studied extensively as a potential therapy targeting KLF5 in other cancer types, such as endometrial, prostate and breast cancer, and some metformin cancer studies have sought to target other gene pathways such as the PI3K/Akt/mTOR pathway." (PMID 31401336, 2019).
breast carcinoma (continued). "High KLF5 expression is an unfavorable prognostic marker correlated with shorter survival for breast cancer patients." (PMID 29348684, 2018). "Estrogen induces the expression of estrogen responsive finger protein (EFP), an E3 ubiquitin ligase which leads to degradation of KLF5 in breast cancer cells." (PMID 30337927, 2018). "Reportedly, kruppel-like factor 5 (KLF5), as a transcription factor, can boost breast cancer cell proliferation, and activate sox4 or HIF-1α transcription via binding to GC-rich DNA sequences, resulting in lung cancer proliferation." (PMID 29773900, 2018). "We previously reported that KLF5 promotes breast cancer cell proliferation, survival, migration, invasion and tumorigenesis." (PMID 29348684, 2018). "We previously found that KLF5 promotes breast cancer cell proliferation, migration and invasion by upregulating the expression of FGF-BP, mPGES1, and TNFAIP2 and down-regulating the expression of p27." (PMID 28437471, 2017). "Previously, KLF5 was reported to promote breast cancer proliferation, migration and invasion in part by upregulating the transcription of TNFAIP243." (PMID 29146991, 2017). "The Weinberg group reported that high KLF5 expression is one of the nine characteristics of high-level, ER-negative, undifferentiated breast cancers." (PMID 28030791, 2017). "In breast cancer, KLF5 plays an important role in tumorigenesis and high expression level of KLF5 is positively correlated with poor survival rate of breast cancer patients." (PMID 28437471, 2017). "The expression of KLF5 is correlated with different hormone status in different breast cancer subtypes." (PMID 28437471, 2017). "As a crucial factor that promotes TNBC cell proliferation and survival, KLF5 has been reported to play important roles in breast cancer progression." (PMID 28030791, 2017). "Previously, we demonstrated that MIF can block KLF5 induction by progesterone in PR-positive breast cancer cells and down-regulate KLF5 expression in TNBC cells by inducing miR-153 expression." (PMID 28030791, 2017). "We previously have reported KLF5 promotes TNBC cell proliferation, survival, migration and invasion via regulating a variety of target genes; however, how KLF5 is regulated in breast cancer needs to be further elucidated." (PMID 28437471, 2017). "Breast cancer patients with higher KLF5 expression have poorer prognosis and significantly shorter survival than those with lower KLF5 expression." (PMID 28030791, 2017). "TRIM25 has also been shown to be regulated by estrogen receptor alpha in breast cancer and to mediate ubiquitination and degradation of two transcription factors: KLF5 and ZFHX3." (PMID 27626314, 2016). "Nevertheless, ATXN3L increased the KLF5 protein stability and inhibited the expression of KLF5 downstream target genes, such as p21 and p27, and promote basal type breast cancer cell proliferation." (PMID 26079537, 2015). "Collectively, our findings not only identify BAP1 as the DUB for KLF5, but also reveal a critical mechanism that regulates KLF5 expression in breast cancer." (PMID 26419610, 2015). "KLF5 is a known oncogenic transcription factor in breast cancer that promotes breast cancer cell proliferation and survival partially by inducing the transcription of FGF-BP1 and mPGES1." (PMID 25970772, 2015). "Taken together, these results demonstrate that BAP1 promotes HCC1806 breast cancer tumorigenesis partially by stabilizing KLF5." (PMID 26419610, 2015). "The transcription factor KLF5 is highly expressed in basal-like breast cancer and promotes breast cancer cell proliferation, survival, migration and tumour growth." (PMID 26419610, 2015). "Our previous studies suggest that KLF5 promotes breast cancer cell proliferation by regulating a number of target genes, such as p21, p27, Cyclin D1, FGF-BP and mPGES1." (PMID 26079537, 2015).